IGF1 (insulin like growth factor 1)
Diseases named in the same sentence as IGF1 in open-access papers (continued):
Sharing a sentence is not in itself a finding about the gene and the disease.
breast cancer (continued). "One study from the Women’s Health Initiative presented results for estradiol with and without adjustment for free IGF-1 and insulin; positive associations with postmenopausal breast cancer appeared stronger with adjustment for both IGF-1 and insulin." (PMID 38363402, 2024). "Secretion of free fatty acids as well as cytokines and growth factors, including Monocyte chemoattractant protein 1 (MCP-1), C-C motif chemokine ligand 5 (CCL5), and Insulin-like growth factor 1 (IGF-1), also promote breast cancer cell invasion and proliferation." (PMID 38473978, 2024). "Overall, these data suggested that CXCL1 might induce autophagy by regulating the IGF1/IGF1R signaling in breast cancer." (PMID 39394189, 2024). "In breast cancer, systematic analysis by flow cytometry cell sorting of single-cell suspensions of tumor cells, non-immune stromal cells, and macrophages identified TAMs and CAFs as the main sources of IGF1/IGF2 ligands in the breast tumor microenvironment." (PMID 38892104, 2024). "Basic research revealed that long-term exposure to high insulin levels promotes breast cancer progression either directly through insulin receptor isoform A and insulin-like growth factor 1 (IGF-1) receptor activation or indirectly through alternation in the circulating estrogen levels." (PMID 36562831, 2023). "However, excessive IGF-1 levels or altered IGF signaling can contribute to breast cancer development." (PMID 37575755, 2023). "Furthermore, these concordant NHS2 and CTS findings are consistent with numerous preclinical and clinical studies examining the role of the IGF-1 axis in driving HR+ breast cancers." (PMID 36331687, 2023). "Also, the gene expression pattern induced by IGF1 predicts poor outcomes in patients with breast cancer." (PMID 37686596, 2023). "In contrast, a weaker impact of IGF-1 on breast cancer mortality was observed in our study, although this association could not be validated in multi-state models." (PMID 38000092, 2023). "The objective of this study was to determine the correlation between cytotoxic T lymphocyte-associated protein-4 (CTLA-4) expression in peripheral blood and insulin-like growth factor-1 (IGF-1) serum level as biomarkers for predicting trastuzumab treatment efficacy in HER-2 positive breast cancer." (PMID 38406785, 2023). "In addition to IGF-1, estrogen is critical in breast cancer, and adiponectin is receiving increasing attention in pancreatic cancer; leptin and adiponectin have been relatively less studied in endocrine-related cancers." (PMID 36755926, 2023). "In the mice receiving combination therapy, TQ and IF treated breast cancer in an additive way without causing liver or kidney toxicity due to decreased levels of glucose, IGF-1, and leptin and increased levels of β-hydroxybutyrate." (PMID 38202341, 2023). "In the multi-state survival analysis, we further found that CRP was mainly associated with invasive breast cancer and the transition from cancer incidence to mortality, while testosterone and IGF-1 were more likely to impact the early state of breast cancer development." (PMID 38000092, 2023). "Aberrant activation of IGF-1 signaling has been documented in breast cancer tissues." (PMID 37511200, 2023). "A case-control study also showed that high IGF-1 levels may be a crucial factor in the progression of benign breast disease to breast cancer." (PMID 38000092, 2023). "Similarly, borderline different effect sizes of IGF-1 on the transitions between event-free to invasive breast cancer, and invasive breast cancer to death from breast cancer were also observed (P = 0.064)." (PMID 38000092, 2023). "Finally, the role of nutritionists in advising breast cancer patients to consider calorie restriction to lower IGF-1 levels is explored." (PMID 38001584, 2023). "In breast cancer, IGF-1 levels were found to strongly correlate with the MIB-1 index." (PMID 36498723, 2022).
breast cancer (continued). "Using two-step MR, we identified IGF-1, SHBG, testosterone, age at menarche and age at menopause as plausible mediators based on the effect of childhood body size on these traits, and their effect on breast cancer risk." (PMID 35396499, 2022). "In addition, tamoxifen up-regulates the production of transforming growth factor B (TGFb), a factor that inhibits tumor cell growth, and down-regulates insulin-like growth factor 1 (IGF-1), a factor that stimulates breast cancer cell growth." (PMID 35745897, 2022). "Elevated IGF-1 and IGBP3 have both recently been affirmed to be risk factors for breast cancer." (PMID 36672557, 2022). "In breast cancer models NR2F1-AS1 increased IGF-1 expression and tumor formation." (PMID 35597813, 2022). "Obesity increases systemic levels as well as cellular secretion of many cytokines and adipokines including leptin, IL6, TNFα, IGF1, fatty acid binding protein 4 (FABP4), and resistin, which are all involved in regulating the pathways associated with the development of CSCs in breast cancer tissue." (PMID 36010901, 2022). "Among these, CXCL12, ESR1, IGF1, and FOS were associated with breast cancer survival." (PMID 35463082, 2022). "Thus, to our knowledge, this is the first study demonstrating an IGF-1 induced localization of SRSF-1 in breast cancer and its ability to regulate FASN expression." (PMID 36096767, 2022). "Thus, the present study identifies the IGF-1-IGF-1R-mTOR axis as an integral signaling axis in the regulation of FASN in breast cancer." (PMID 36096767, 2022). "The IGF-1-ER+ breast cancer association, which was not robust to multiple testing correction in two-sample MR but was supported by mediation analyses, is consistent with both observational and MR data." (PMID 36558416, 2022). "For instance, WISP2 may suppress EMT in breast cancer, on the other hand WISP2 silencing promotes a stem-like cell phenotype and the loss of the IGF1 and EGF mitogenic effect in ER-α positive breast cancer cells." (PMID 35326638, 2022). "Similarly, Christopoulos also demonstrated an important role of the IGF-1 system and its receptors in the occurrence, progression and metastasis of breast cancer." (PMID 35035440, 2022). "There are several possible mechanisms explaining the critical role of visceral obesity in breast cancer prognosis, including increased circulating levels of estrogen, high circulating insulin and insulin-like growth factor 1, altered adipokine levels, and systemic and tissue-level inflammation." (PMID 36203426, 2022). "This study aims to explore the efficacy of ultrasound combined with the molybdenum target detection mode in clinical diagnosis and evaluation of the development of breast cancer and to perform IGF-1 and IGF-2 detection for patients with different degrees of disease." (PMID 35845730, 2022). "Thus, we aimed to determine if the IGF-1-mTORC1 axis affects the subcellular localization of SRPK2 in breast cancer cells." (PMID 36096767, 2022). "Based on our results obtained using GEO disease data and molecular docking analysis, we suggest that the intervention of formononetin in breast cancer may be achieved by regulating IGF1, ESR1, and CXCL12." (PMID 35463082, 2022). "The study investigates the diagnostic efficacy of ultrasound combined with the molybdenum target mode in breast cancer staging and the relationship between blood flow parameters and the expression of insulin-like growth factor 1 (IGF-1) and factor 2 (IGF-2) and prognosis." (PMID 35845730, 2022). "Breast cancer patients with disease and illness development situation may be affected by the IGF-1 and IGF-2 expression." (PMID 35845730, 2022). "These current findings establish a potential IGF-1-mTORC1-SRPK2-FASN axis in breast cancer, which could be a potential therapeutic target for cancers that overexpress FASN and components of the IGF-1R pathway." (PMID 36096767, 2022).
breast cancer (continued). "A randomised controlled trial conducted among 100 breast cancer survivors, assigned either to exercise or usual care, showed an improvement in BMI and levels of circulating biomarkers, i.e., insulin, IGF-1, adiponectin and leptin, in the exercise group after the exercise intervention." (PMID 36077690, 2022). "Similarly, frequency of IGF-1 immunoreactivity among different molecular subtypes of breast carcinoma was mimicking that observed in ANGPTL4." (PMID 35366286, 2022). "Crosstalk between IGF-1 and ER is known to regulate gene expression in breast cancer cells, but the underlying mechanisms are not fully understood." (PMID 33816477, 2021). "However, puromycin induced apoptosis in breast cancer cells mediated by insulin-like growth factor 1 (IGF-I)." (PMID 34224310, 2021). "Since IGF-1 stimulates cell growth and differentiation and inhibits apoptosis, the presence of this hormone in milk has the potential to influence the development of cancerous tumors and the development of breast cancer." (PMID 34959971, 2021). "The top 20 possible drugs that could reverse the breast cancer lung metastasis signature were presented, including IGF-1 inhibitor, mTOR inhibitor, PI3K inhibitor, SRC inhibitor, aurora kinase inhibitor, and JAK inhibitor." (PMID 35111673, 2021). "Additionally, diabetes can directly affect breast cancer by altering related molecules, such as insulin, IGF-1 and inflammatory markers." (PMID 33842335, 2021). "AI therapy has been shown to result in increased IGF-1 levels and an increased incidence of arthralgia in women treated for breast cancer, while tamoxifen reduced IGF-1 levels and the overall incidence of musculoskeletal side effects when used as adjuvant therapy." (PMID 33910628, 2021). "In addition, IGF-1 and IGF binding protein 3 are also associated with breast cancer risk, progression, recurrence, and the probability of survival in African American women." (PMID 35008602, 2021). "RFX1 is a key player in the suppression of IGF-1 mediated breast cancer cell proliferation." (PMID 33964962, 2021). "From the results obtained the authors concluded that there is a probable causal relationship between circulating IGF-1 concentrations and breast cancer regardless of menopausal status." (PMID 33816477, 2021). "Higher circulating IGF-1 levels are indicative of higher risk of breast cancer in premenopausal women, and it has been reported that IGF-1 stimulates proliferation of breast cancer cells." (PMID 34299089, 2021). "SHP1, with the help of RFX1, could inhibit IGF1-induced cell proliferation, thereby accentuating survival in breast cancer cell lines MCF-7 and ZR-75–1." (PMID 33964962, 2021). "Indeed, TRPV2 was first identified as being a growth factor-regulated channel as it mediated IGF-1 induced Ca2+ entry in breast cancer cells." (PMID 34936030, 2021). "Furthermore, higher IGF-1 levels are related to reduced overall survival in breast cancer patients treated with endocrine therapy." (PMID 33910628, 2021). "Tamoxifen lowers plasma IGF-1 levels in individuals with breast cancer, which may contribute to its antitumor action." (PMID 33910628, 2021). "We reviewed the main findings recent years on the principal molecular actors that are involved in the interactions between MetS and breast cancer biology, including leptin, adiponectin, insulin and IGF-1, Angiotensin II and Calcium and, cholesterol and lipoprotein." (PMID 33842335, 2021). "Finally, a non-registered clinical trial on postmenopausal breast cancer survivors evaluated the effect of 3 mg of melatonin on breast cancer biomarkers such as estradiol and insulin-like growth factor I (IGF-1)." (PMID 33572626, 2021). "When stratified by levels of insulin and the IGF axis biomarkers, participants with low insulin (HR: 1.42; 95% CI: 1.11–1.82), low C-peptide (HR: 1.41; 95% CI: 1.10–1.80), and low IGF1/IGFBP3 ratio (HR: 2.55; 95% CI: 1.18–5.49) exhibited increased risk of breast cancer recurrence." (PMID 34456877, 2021).
breast cancer (continued). "Additionally, the IGF-1R inhibitor PQIP diminishes the breast cancer cell-induced osteolysis in a bone metastasis mouse model by inhibiting the IGF-1/IGF-1R/AKT axis-dependent osteoclast formation." (PMID 34064589, 2021). "Similarly, in breast cancer cells, IGF1 stimulates mitochondrial homeostasis by increasing oxidative phosphorylation to produce ATP required for proliferation." (PMID 33673232, 2021). "In addition, proliferation of breast cancer is enhanced by insulin-like growth factor 1 (IGF-1) and epidermal growth factor (EGF), which stimulate signaling through the MAPK and PI3K/AKT pathways by activation of IGF-1R and EGFR receptors, respectively." (PMID 34462889, 2021). "Women with IGF-1 concentrations in the top 20% were shown to have a 1.24-fold increased chance of developing breast cancer compared to those in the bottom 20%, after adjustments for factors including age, body mass index and concentrations of other hormones and proteins in the blood." (PMID 33557137, 2021). "Targeting the IGF-1/IGF-1R/S100A7 pathway may therefore represent a further useful approach for blocking disease progression in breast cancer patients with dysregulated IGF-1 signaling." (PMID 33557316, 2021). "Calcium and vitamin D found in dairy products may also increase the circulation of IGF-1, which plays an important role in cell proliferation and carcinogenesis, leading to the development of breast cancer." (PMID 33430001, 2021). "The consortium reported significant associations of breast cancer risk with total testosterone, SHBG, IGF-1 and total and calculated free oestradiol in pre-menopausal women and with total testosterone, SHBG and IGF-1, as well as with total and calculated free oestradiol, in post-menopausal women." (PMID 33864017, 2021). "When comparing estrogen receptor positive (ER+) and negative (ER-) breast cancers separately IGF-1 was found to be only associated with an increased risk of ER+ breast cancer." (PMID 33557137, 2021). "In breast cancer IGF-1 has been shown to increase aromatase activity." (PMID 33816477, 2021). "Mendelian randomization was used to analyze data from 265 gene variants known to be associated with IGF-1 concentrations in 122,977 women with breast cancer and 105,974 women without cancer." (PMID 33557137, 2021). "IGF1 participates in the growth and invasiveness of breast cancer." (PMID 34253194, 2021). "The GH/IGF-1 axis plays an integral role in breast development; furthermore, when GH and IGF-1 levels are experimentally perturbed, hyperplastic lesions may develop, increasing the chances of mammary carcinoma." (PMID 33910628, 2021). "IGF1 has been recognized as a major regulator of mammary epithelial cell and breast cancer growth." (PMID 32391121, 2020). "Surprisingly, we did not observe a statistically significant association of IGF1 with breast cancer-specific mortality or breast cancer recurrence." (PMID 32974138, 2020). "In one large follow-up study on breast cancer in postmenopausal women, serum levels of IGF-2, but not IGF-1, were positively associated with oestrogen receptor-positive breast cancer risk." (PMID 33114046, 2020). "However, chemerin treatment recovered the reduced E-cadherin expression level in breast cancer cells treated with TGF-β or IGF-1." (PMID 32325994, 2020). "Using conditional logistic regression, we estimated the association between IGF-1 and IGFBP-3 levels and breast cancer risk and examined whether this risk differed by predicted absolute breast cancer risk based on pedigree models." (PMID 33092613, 2020). "However, chemerin treatment recovered the reduced E-cadherin expression in breast cancer cells treated with TGF-β or IGF-1." (PMID 32325994, 2020). "It is possible that after the surgery of breast cancer, IGF1 may exhibit a protective function in overall survival via its favorable effects on cell survival and metabolic control." (PMID 32974138, 2020). "IGF1 signaling regulates proliferation of breast cancer cells." (PMID 32444795, 2020).
breast cancer (continued). "The MCF7 cell line is a model breast cancer cell line that is robustly responsive to IGF1." (PMID 32444795, 2020). "The overall association between IGF-1 or IGFBP-3 elevation (≥ median in controls) and breast cancer risk was elevated, but not statistically significant (IGF-1 OR = 1.37, 95% CI = 0.66–2.85; IGFBP-3 OR = 1.62, 95% CI = 0.81–3.24)." (PMID 33092613, 2020). "In this study, we investigated the promotive effects of lncRNA NR2F1‐AS1 on breast cancer angiogenesis both in vitro and in vivo, declaring the potential mechanism through inducing the expression of IGF‐1 in breast cancer cells and then activating IGF‐1R/ERK pathway in endothelial cells." (PMID 32548873, 2020). "For example, given the incidence of breast cancer-specific mortality between the two groups with low or high IGF1 levels, in order to achieve a statistical power of 0.80, the sufficient overall sample size and number of events should be around 2,800 and 80, respectively." (PMID 32974138, 2020). "Estrogen, progesterone and insulin-like growth factor 1 (IGF-1) levels in cord blood vary by birthweight and preeclampsia exposure; they may set the baseline concentrations of hormones for breast cancer." (PMID 32133286, 2020). "Notably, Walsh and his colleague pointed out that IGF1 increased invasive potential of MCF 7 breast cancer cells." (PMID 33298061, 2020). "In the case of breast cancer more specifically, the mechanisms that have been purposed as key factors in this interaction include leptin, adipose tissue inflammation, insulin and insulin growth factor(IGF-1) and sex hormones." (PMID 33371214, 2020). "In addition, high IGF1R expression and elevated circulating IGF1 levels were correlated with improved response to IGF1R-targeted therapies in clinical trials for non-breast cancers." (PMID 32391121, 2020). "In addition to the chemo-attractant and macrophage-recruiting properties of other adipokines, adiponectin has been shown to cross-talk with the IGF-1 axis and thereby potentiate its growth-promoting effect on breast cancer cells." (PMID 32736587, 2020). "IGF‐1 could also act as one of the pro‐angiogenetic factors through inducing VEGF or NO in breast cancer microenvironment." (PMID 32548873, 2020). "Interestingly, PI3K has been confirmed as a downstream target of insulin-like growth factor-1, which promotes breast cancer cell migration." (PMID 32818022, 2020). "Therefore, increased accumulation of estrogen and IGF–1 contributes to breast cancer development and progression." (PMID 32093283, 2020). "We found an overall increased breast cancer risk for IGF-1 or IGFBP-3 elevation, although it was not statistically significant (≥ median compared to <: IGF-1 OR = 1.37, 95% CI = 0.66–2.85; IGFBP-3 OR = 1.62, 95% CI = 0.81–3.24)." (PMID 33092613, 2020). "Furthermore, several epidemiologic studies discovered an increased risk of breast cancer with higher levels of IGF-1 and the ratio of IGF-1 to IGFBP-3." (PMID 31816813, 2019). "On the other hand, another study showed that one year of high-dose vitamin D supplementation did not significantly alter serum IGF-1 among women at a high risk of breast cancer nor in prediabetes subjects." (PMID 31281588, 2019). "In addition, higher plasma concentrations of arginine were correlated with lower estradiol and insulin-like growth factor 1 concentrations in premenopausal women, linking arginine to known mechanisms leading to breast cancer development." (PMID 31547832, 2019). "Insulin and insulin-like growth factor-1 (IGF1) have important roles in breast cancer development." (PMID 31771180, 2019). "The consumption of milk and/or dairy products, due to the high saturated fat content and insulin-like growth factor 1 (IGF-1), has been hypothesized to influence the risk for breast cancer." (PMID 31877693, 2019). "We have also demonstrated that IGF1 contributed to the proliferation of breast cancer cells." (PMID 30185144, 2018).